IL37 (interleukin 37)
Diseases named in the same sentence as IL37 in open-access papers (continued):
Sharing a sentence is not in itself a finding about the gene and the disease.
psoriasis (continued). "Published data has been demonstrated that IL-37 can alleviate the symptoms of DSS colitis and inflammatory process in psoriasis by inhibiting the expression of inflammatory cytokines in these diseases and reduce liver inflammatory injury via effects on hepatocytes and non-parenchymal cells." (PMID 25226272, 2014). "However, intradermal injection of IL-37 in a mouse model with imiquimod-induced psoriasis showed a protective effect without statistical significance, and lower levels of IL-37 in human psoriasis lesions compared to healthy skin." (PMID 39126010, 2024). "Also, immunohistochemical analysis has shown that IL-37 expression in the granular layer of the epidermis is absent from psoriasis lesions." (PMID 37834081, 2023). "Therefore, the strategy to control IL-37 expression using AHR modulators such as tapinarof and GFF should be beneficial for the treatment of aging as well as inflammatory skin diseases including AD and psoriasis." (PMID 35663970, 2022). "IL-1 family member IL-37 can interact with the IL-18 receptor, and IL-37 overexpression in human keratinocytes inhibits the production of CXCL8, IL-6, and S100A7, suggesting that IL-37 may play an immunosuppressive role in psoriasis pathogenesis." (PMID 33055429, 2020). "Researchers showed that IL-37 transgenic mice (IL-37tg) can markedly reduce clinical manifestations of DSS colitis, ischemia–reperfusion injury, obesity-induced inflammation, LPS-induced shock and psoriasis, and ameliorate their inflammatory cytokine productions." (PMID 25226272, 2014).
autoimmune disease (56 papers, 2011 to 2025). A disorder resulting from loss of function or tissue destruction of an organ or multiple organs, arising from humoral or cellular immune responses of the individual to their own tissue constituents. "Of note, there is limited evidence suggesting that IL-37 levels are negatively associated with age in infectious and autoimmune disease settings, including eumycetoma infection, Hashimoto’s thyroiditis, and multiple sclerosis." (PMID 34367169, 2021). "The IL-37 gene is polymorphic, and some polymorphisms have been associated with the development of inflammatory and autoimmune diseases." (PMID 34199391, 2021). "A growing body of evidence indicates that IL-37 inhibits inflammation reactions in autoimmune diseases, which are commonly associated with disease activities." (PMID 25226272, 2014). "More recently, increased il-37 levels have been associated with many chronic inflammatory and autoimmune diseases such as systemic lupus erythematosus and Guillain-barré syndrome in humans." (PMID 24733959, 2014). "Previous clinical studies have implicated that IL-37 SNP rs3811047 associated with the susceptibility to gastric cardiac adenocarcinoma, autoimmune diseases including autoimmune thyroid disease (AITD), ankylosing spondylitis (AS) and disease activity of rheumatoid arthritis (RA)." (PMID 28076390, 2017). "Interleukin-37 (IL-37) is a potent anti-inflammatory cytokine that plays a crucial protective role in cancer, autoimmune diseases, and inflammatory diseases though its unique dual intracellular and extracellular action pathways." (PMID 41293155, 2025). "Abnormal IL-37 expression is observed in a variety of diseases, including autoimmune diseases, cardiovascular diseases, neurological disorders, liver disorders, skin diseases, asthma, infections, and cancer." (PMID 41293155, 2025). "IL-37 is highly expressed in various autoimmune diseases, such as rheumatoid arthritis, systemic lupus erythematosus, and Sjögren syndrome." (PMID 41208111, 2025). "IL-37 is a protective cytokine against acute and chronic inflammatory diseases; in fact, in autoimmune diseases, the levels of IL-37 are abnormal compared to those of healthy patients." (PMID 36362030, 2022). "The role of IL-35 and IL-37 have been well reviewed in autoimmune diseases, e.g. rheumatoid arthritis, Hashimoto’s thyroiditis, allergic respiratory diseases and cardiovascular diseases." (PMID 36483045, 2022). "Previous research has shown the function of IL-37 in autoimmune diseases, including systemic lupus erythematosus, colitis, sepsis, asthma, and cancer." (PMID 35741608, 2022). "Especially in recent years, extracellular IL-37 has been confirmed to exert a regulatory role in autoimmune disease by inhibiting the activation of NLRP3 inflammasome." (PMID 36418383, 2022). "In numerous recent studies, the anti-inflammatory effects of IL-37 have been described in many autoimmune diseases, colitis, and tumors." (PMID 35741608, 2022). "In other studies, therapeutic effects of IL-37 on allergic diseases, autoimmune diseases, and other immune system diseases have been reported." (PMID 35741608, 2022). "Extracellular IL-37 has been confirmed to exert a regulatory role in autoimmune disease by inhibiting the activation of NLRP3 inflammasome." (PMID 36418383, 2022). "Although IL-37tg mice are protected from the development of autoimmune diseases, IL-37 expression in these disorders is mainly high and positively associated to the disease activity." (PMID 34248996, 2021). "The anti-inflammatory cytokine IL-37 has been shown to mitigate immune responses in experimental inflammatory conditions and autoimmune diseases." (PMID 34029331, 2021). "In recent years, a role for IL-37 has been discovered in several different diseases, such as autoimmune diseases, cancer, and inflammatory diseases." (PMID 34248996, 2021).
autoimmune disease (continued). "Studies have shown elevated expression of IL-37 and its positive correlations with the disease activity parameters in patients with autoimmune diseases such as RA, systemic lupus erythematosus, AS, and systemic juvenile idiopathic arthritis." (PMID 33652679, 2021). "IL-37 is a recently discovered cytokine in the IL-1 family exerting broad protective effects on inflammatory diseases, autoimmune diseases, and cancer." (PMID 34248996, 2021). "In contrast, IL-37 is known to be negatively involved in the development and pathogenesis of autoimmune diseases." (PMID 33652679, 2021). "In autoimmune diseases, IL-37 and IL-10 contribute to the tolerance process by suppressing MHC class II and inflammation." (PMID 32560266, 2020). "Here, we discuss, for the first time, the current knowledge of IL-37 in autoimmune disease SS and propose a new therapeutic role." (PMID 32560266, 2020). "IL-37 is an anti-inflammatory cytokine that broadly suppresses innate and acquired immunity, and is abnormal in patients with autoimmune disorders." (PMID 32560266, 2020). "IL-37 is a natural inhibitor of innate and acquired immunity, and the level is abnormal in patients with autoimmune disorders." (PMID 32560266, 2020). "These advances indicate the promising therapeutic potential of IL-37 in conditions such as autoimmune disorders, ischemia-reperfusion injury, transplant rejection, and allergic diseases." (PMID 32104716, 2020). "IL-37, as an IL-1 family cytokine, has been demonstrated to be an immunosuppressive factor in many inflammatory and autoimmune diseases 1,9,26." (PMID 32226541, 2020). "Overall, we investigated IL-37 induction as a novel therapeutic mechanism for inflammatory and autoimmune diseases along with the possible signaling pathways involved in regulating IL-37 expression by autophagy-modifying reagents." (PMID 32104716, 2020). "Recent studies have shown abnormal IL-37 expression in autoimmune diseases, including Behcet's disease, and functional analysis has shown that IL-37 expression is negatively correlated with the development and pathogenesis of BD." (PMID 30984205, 2019). "These augmented levels of IL37 in inactive phases of autoimmune diseases have been interpreted as a compensatory attempt that is physiologically activated by the body to counteract excessive ongoing immunoinflammatory responses." (PMID 31861585, 2019). "Interleukin-37 (IL-37) is unique in the IL-1 family since it broadly suppresses innate immunity and elevates in humans with inflammatory and autoimmune diseases." (PMID 30728750, 2019). "In spite of these data of IL37 in autoimmune diseases, only a limited number of studies have evaluated the possible role of this cytokine in MS." (PMID 31861585, 2019). "In rodent models of autoimmune diseases, the intra-articular injection of an adenovirus vector expressing IL37 into the knee joints of mice with type II collagen-induced arthritis (CIA) markedly down-regulated the clinical and histological signs of arthritis." (PMID 31861585, 2019). "Following up studies have shown that IL-37 is closely related to inflammatory diseases and autoimmune diseases." (PMID 29805973, 2018). "It has been observed that IL-37 was elevated in humans with inflammatory and autoimmune diseases, such as Graves’ disease, multiple sclerosis, and rheumatoid arthritis, although the concentrations of IL-37 in the circulation of healthy humans are low." (PMID 30563054, 2018). "Previous studies have demonstrated that IL-37 acts as an immune mediator to restrain the inflammatory response of many inflammatory and autoimmune diseases." (PMID 29566725, 2018). "In recent years, accumulating studies have found that IL-37 is closely related to inflammatory and autoimmune diseases, including SLE, RA, and AOSD." (PMID 30305171, 2018).
autoimmune disease (continued). "Studies have confirmed that IL-37 plays an important role in many diseases such as infectious diseases, metabolic diseases, ischemia-reperfusion injury, autoimmune diseases, and tumors." (PMID 29805973, 2018). "IL-37 plays a role in protecting the body against endotoxin shock, ischemia-reperfusion injury, autoimmune diseases, and cardiovascular diseases." (PMID 29805973, 2018). "In recent years, IL-37 has been found to play an important regulatory role in the development of a variety of inflammatory diseases, autoimmune diseases, and tumors." (PMID 29805973, 2018). "In recent years, the inhibitory activity of IL-37 has also been investigated in autoimmune diseases." (PMID 29566725, 2018). "In striking contrast with experimental RA, but in line with the results obtained in patients with other autoimmune disease, studies performed in RA patients revealed higher serum and plasma levels of IL-37 compared to normal and OA controls." (PMID 30886947, 2017). "Our previous studies have demonstrated that IL-37 plays as an immune mediator to restrain the inflammatory response of autoimmune diseases in SLE and GD." (PMID 25627863, 2015). "It has been testified that IL-37 inhibited the excessive inflammatory response in autoimmune diseases." (PMID 25226272, 2014). "IL-37 can decrease the production of proinflammatory cytokines and protect mice from inflammatory and autoimmune diseases." (PMID 24733959, 2014). "And higher levels of serum IL-37 were detected in patients with autoimmune diseases, such as RA, IBD, and SLE." (PMID 24174711, 2013). "IL-37 is a potential therapeutic target due to its protective function in the pathogenesis and progression of metabolic disorders, cancer, and inflammatory and autoimmune diseases." (PMID 41293155, 2025). "An abnormal level of IL-37 is observed in patients with inflammatory and autoimmune diseases." (PMID 37024713, 2023). "IL-37 is an anti-inflammatory cytokine involved in inflammatory and autoimmune diseases." (PMID 37853488, 2023). "IL-37, a special member of IL-1 family, can generally suppress innate immunity and acquired immunity and, consequently, it plays an important role in a variety of inflammatory and autoimmune diseases." (PMID 36002836, 2022). "In tumors and some autoimmune diseases, IL-37 has exhibited its powerful anti-inflammatory ability." (PMID 35741608, 2022). "However, dysregulated/upregulated IL-37 expression is observed in autoimmune diseases, including rheumatoid arthritis, psoriasis, Grave’s disease, gestational diabetes mellitus, systemic lupus erythematosus and inflammatory bowel disease." (PMID 36483045, 2022). "In addition, genome editing technology as a new technology is now widely used in treating autoimmune diseases, for example, by genome editing IL-37 can enhance mesenchymal stem cells (MSCs) thus providing a new and reliable approach for the treatment of SLE." (PMID 36176425, 2022). "Therefore, this review summarized the broad anti-inflammatory properties of IL-37 in inflammatory diseases, autoimmune diseases, and cancer based on the research progress in recent 5 years." (PMID 34248996, 2021). "Thus, further investigations are necessary to discover the different mechanisms used by IL-37 in different autoimmune disorders." (PMID 34248996, 2021). "Therefore, this review provides an updated view of the role of IL-37 in human health and disease, and discusses the potential of IL-37 as a therapeutic target and biomarker in inflammatory diseases, autoimmune diseases, and cancer." (PMID 34248996, 2021). "IL-37, on the other hand, is one of the newest members of interleukin family and its concentration was shown to be increased in patients with different inflammatory and autoimmune diseases." (PMID 33902634, 2021). "However, the actual information on IL-37 highlights its potential role as a promising candidate in the treatment of inflammatory diseases, autoimmune diseases, and cancer." (PMID 34248996, 2021).
autoimmune disease (continued). "However IL-37 plays an important anti-inflammatory and immunomodulatory capacity in a variety of inflammatory and autoimmune diseases." (PMID 32849879, 2020). "We can speculate that the upregulation of IL37 might reflect a general, adaptive protective mechanism, common to multiple autoimmune diseases, to compensate for a system more prone to inflammation." (PMID 31065051, 2019). "IL-37, as a recently identified member of IL-1 family, has been shown an important anti-inflammatory cytokine in the development of many inflammatory diseases, autoimmune diseases and tumors." (PMID 30305171, 2018). "It is therefore reasonable to speculate that such increase of IL-37 may be a compensatory mechanism to counteract the effector immune response, likely occurring also in other autoimmune diseases." (PMID 30886947, 2017). "In accordance with such opinion, several studies have shown that IL-37 could restrain autoimmune diseases." (PMID 27941849, 2016). "Based on the important role of IL-37 in the suppressive activity of CD4+CD25+ Tregs, it may be feasible to use IL-37 as an immunotherapy for autoimmune diseases, allergies, allograft rejection or even sepsis." (PMID 27941849, 2016). "Moreover, Th17 and some cytokines such as IL17, IL21, IL27, IL35, and IL37 are recognized well in autoimmune diseases, though their possible roles as therapeutic target in GBS need to be further explored." (PMID 25614713, 2014). "Interleukin 37 (IL-37), a recently identified member in the interleukin (IL)-1 class, is essential for controlling innate inflammation and inhibiting acquired immunological responses and, therefore, it shows great potential for treating a variety of autoimmune diseases and inflammatory diseases." (PMID 36362351, 2022). "IL-38, in the same family as IL-37, may be expressed in autoimmune diseases through genome editing." (PMID 34539413, 2021). "Finally, IL-37 may have a potential ability to reduce excessive inflammation since it is aberrantly expressed in patients with inflammatory diseases, autoimmune diseases, and cancer, thus, it may be used as a marker for different types of diseases." (PMID 34248996, 2021). "In addition, the inhibitory effect of IL-37 could be a new therapeutic strategy in the treatment of inflammatory pSS autoimmune diseases." (PMID 32560266, 2020). "Thus, we speculate that IL-37 might be useful for the treatment of autoimmune disease, allergy as well as allograft rejection and GVHD in Treg-targeted strategy." (PMID 27941849, 2016). "The reasons for these discrepancies concerning IL-37 expression between uveitis and other autoimmune diseases is not clear and deserves further study." (PMID 27775096, 2016). "In vivo, it has been shown that the expressions of IL-37 were up-regulated by inflammatory activity and pro-inflammatory cytokines in autoimmune diseases, such as rheumatoid arthritis and SLE, especially in active stage of autoimmune disease." (PMID 25226272, 2014).